FOXP3 (forkhead box P3)
Diseases named in the same sentence as FOXP3 in open-access papers (continued):
Sharing a sentence is not in itself a finding about the gene and the disease.
lupus nephritis (25 papers, 2013 to 2025). Glomerulonephritis in the context of systemic lupus erythematosus. "Treatment was also associated with a decrease in the intra-renal expression of FoxP3+, with the number of FoxP3+ cells being unexpectedly increased in the setting of murine lupus nephritis." (PMID 31548534, 2017). "CLT has also been reported to alleviate murine lupus nephritis via inducting CD4+Foxp3+ regulatory T cells." (PMID 39494325, 2024). "The increased activity of Th1 and reduced activity of Treg, in this study represented by pro-inflammatory IFNγ levels and FOXP3 mRNA expression, has proven to be related to the development of lupus nephritis." (PMID 34386197, 2020). "G-CSF treatment ameliorated lupus nephritis through the preferential expansion of CD4+CD25+Foxp3+ Tregs." (PMID 27846813, 2016). "To investigate the immune modulatory function of macrophages in lupus nephritis we also performed immunohistochemical analysis of forkhead-box-protein P3 (FoxP3)-positive T cells in renal biopsies." (PMID 27091114, 2016). "CD4+Foxp3+IL-17A+ cell infiltration was found in renal biopsy specimens of active lupus nephritis." (PMID 35197962, 2021). "Finally, IL-17A-expressing CD4+Foxp3+ T cells were also detected in renal biopsy specimens of patients with active lupus nephritis." (PMID 32317002, 2020). "Finally, CD4+Foxp3+IL-17A+ cells were infiltrated into the renal biopsy specimens of patients with active lupus nephritis." (PMID 32317002, 2020). "Treg CD4+Foxp3 secretes an abundant amount of cytokines that proliferate CD4 T-cells specific towards nuclear antigen, such as nucleosome, which is known as pathogenic antibody in lupus nephritis." (PMID 30858943, 2019). "As CD4+Foxp3+ nTreg cells had a minimal therapeutic effect on lupus nephritis, we were interested in exploring whether CD8+CD103+ iTreg have therapeutic effect on SLE/lupus nephritis." (PMID 29441062, 2018). "G-CSF treatment ameliorated lupus nephritis, and preferential expansion of CD4+CD25+Foxp3+ Tregs instead of MDSC may be the underlying mechanism." (PMID 27846813, 2016). "Surprisingly, there was no exclusive correlation between FoxP3+ Treg and M2c-like macrophages in renal biopsies from patients with lupus nephritis, but simply an association with higher numbers of macrophages in general." (PMID 27091114, 2016). "In lupus nephritis (LN), mangiferin increases the proportion of CD4+Foxp3+ Tregs and inhibits the mTOR/p70S6K pathway in FasL-deficient B6/gld mice, serving as a therapeutic agent for LN." (PMID 41458964, 2025). "Rapamycin treatment alleviated SLE-like experimental lupus nephritis by the recovery of IL-2 production, which modulated the maintenance and expansion of CD4+FOXP3+ Tregs, in turn inhibiting activated effector T cells." (PMID 36979928, 2023). "Immunohistochemistry of renal biopsy specimens obtained from 6 patients with lupus nephritis and 5 with IgA nephropathy was conducted to detect IL-17A-expressing CD4+Foxp3+ cells." (PMID 32317002, 2020). "To overcome the concern that Foxp3 is unstable in inflammatory conditions, we have studied the functional characteristics of CD8+CD103+ iTreg cells in a lupus nephritis model." (PMID 29441062, 2018). "Using immunohistochemical analysis we analyzed renal biopsies from 68 patients with lupus nephritis (ISN/RPS classes II–V) for infiltration with M1-like (iNOS+/CD68+), M2a-like (CD206+/CD68+), M2c-like macrophages (CD163+/CD68+), and FoxP3+ regulatory T-cells." (PMID 27091114, 2016). "Anyway, target organ pathology in lupus nephritis, is inhibited by the TGFβ producing CD4+FoxP3+ Treg and CD8+FoxP3+ Treg cells induced by histone peptide epitope tolerance therapy, or by targeted nanoparticle therapy induced CD8+ Treg, which are quite different from the cytotoxic CD8 Treg." (PMID 33936042, 2021).
lupus nephritis (continued). "CD4+IL-17A+ cells were detected mainly in the interstitial lesions of kidneys from both patients with lupus nephritis and those with IgA nephropathy, but the majority of the CD4+IL-17A+ cells also showed nuclear/cytoplasmic expression of Foxp3 in patients with lupus nephritis." (PMID 32317002, 2020).
Hepatitis (24 papers, 2011 to 2026). Inflammation of the liver. "In this regards, neonatal thymectomy (NTx) leads to the development of much severe hepatitis in PD-1-deficient mice than in PD-1-intact mice through concurrent loss of FOXP3-expressing Tregs." (PMID 33665689, 2021). "Conversely, the experimental removal of Treg cells or Foxp3 mutations in mice and humans causes systemic autoimmune diseases, including liver inflammation." (PMID 33178216, 2020). "Treg-deficiency due to Foxp3 gene mutation resulted in the histological features of hepatitis which could be ameliorated using gavage feeding DSM 17938." (PMID 38398835, 2024). "In this regard, hepatitis and liver damage, associated with a marked immune infiltration, elevated serum alanine aminotransferase and diminished albumin in Treg cell-depleted Foxp3DTR mice, were undetectable in Foxp3AIDR26TIR1(F74G) mice after 4 weeks of continuous Foxp3 degradation." (PMID 41062655, 2025). "The observation of the preferential Treg expansion in damaged livers prompted us to examine the role of Foxp3+ Treg cells in the regulation of CCl4-induced liver inflammation and fibrosis." (PMID 33178216, 2020). "One striking finding was that ATF3 deficiency depressed Foxp3+ Tregs, whereas it increased ROR+ Th17 cells in IR-induced liver inflammation." (PMID 30185770, 2018). "Disruption of ATF3 downregulated Foxp3 and upregulated RORγt-mediated IL-17A expression in IR-induced liver inflammation." (PMID 30185770, 2018). "In earlier reports, CCR10-expressing CD25+CD4+FOXP3+ Treg cells were identified to be critical for maintaining the potent anti-inflammatory properties in liver inflammation." (PMID 27716621, 2016). "It has been reported that FTY720, a drug used to treat autoimmune hepatitis, could recruit more MDSC, inhibit Th1 cells to produce IFN-γ, activate Foxp3+ Tregs, and decrease liver damage in ConA-induced hepatitis." (PMID 27524863, 2016). "CD25+Foxp3+ CD4 T cells accumulated in the liver in the course of CD8 T cell-mediated hepatitis." (PMID 26599014, 2015). "In this regard, hepatitis and liver damage, associated with a marked immune infiltration, elevated serum alanine aminotransferase (ALT) and diminished albumin in Treg-depleted Foxp3DTR mice, were undetectable in Foxp3AIDR26TIR1(F74G) mice after four weeks of continuous Foxp3 degradation." (PMID 40470210, 2025). "One can speculate that the expanded clonotypes within the Treg_Foxp3 cluster might selectively target the clones distributed to the Th1/CTL cluster, and the balance among those clonotypes could be potentially associated with severity of liver inflammation and MASH." (PMID 39405120, 2024). "In contrast, in an α-GalCer–induced hepatitis mouse model, pharmacological Galectin-3 neutralization could increase the percentage of CD4+CD25+FOXP3+ Treg cells and TGF-β–producing Treg cells among liver-infiltrating cells." (PMID 41477833, 2026). "We have found that DPPS pretreatment significantly enhances percentages of FoxP3+ regulatory CD4+ and CD8+ cells in the livers of mice with ConA-induced hepatitis and enhances the percentage of activated CD69+CD25+ T cells, but decreases percentage of inflammatory IL-17+ and IFN-γ+ T cells." (PMID 33809904, 2021). "The distribution of FOXP3 in HCC was similar to that of cirrhosis, but not to hepatitis caused by the hepatitis B virus (HBV), which suggested that FOXP3 was associated with a high risk of HCC8." (PMID 33116119, 2020). "In contrast, numbers of CD4+ or CD4+CD25+Foxp3+ T cells in the spleen did not significantly change during the course of hepatitis." (PMID 26599014, 2015). "Histological assessment confirmed that significantly more CD8 T cells infiltrated the livers of mice suffering from hepatitis in the absence of Treg and also confirmed that depletion of CD3+Foxp3+ T cells upon DT-application was effective." (PMID 26599014, 2015). "Expression of Foxp3 was not further increased in ST2+ and ST2- Foxp3+ Tregs in liver inflammation." (PMID 38571949, 2024).
dermatitis (23 papers, 2015 to 2026). An inflammatory process affecting the skin. "Foxp3-deficient mice or spontaneous Foxp3 mutant scurfy mice also exhibit severe autoimmune pathologies including dermatitis, lymphoproliferation, and lymphocytic infiltration of multiple organs." (PMID 30936880, 2019). "Loss of Tregs caused by Foxp3 deficiency caused a multi-organ inflammatory response including skin inflammation resembling AD associated with elevated serum IgE levels, eosinophilia, dysregulated Th1 and Th2 cytokine production, and other autoimmune symptoms." (PMID 28218721, 2017). "In conclusion, KO of the CD73 gene reduces dermatitis in Foxp3+Treg-deficient SF mice, which may mainly be due to reduced central and peripheral lymphoproliferation." (PMID 39846845, 2025). "In this study, we report an unexpected finding in the Foxp3+Treg-deficient SF mouse—that KO of the host CD73 gene reduced clinical symptoms, especially dermal inflammation, including ear deformity and dermatitis of the ears and tail." (PMID 39846845, 2025). "Although Treg from Sharpinfl/flK5Cre mice were genetically intact, they displayed reduced expression of Foxp3 and shifted to an activated and short-lived phenotype as dermatitis progressed." (PMID 31462647, 2019). "Since inflammation reduced expression of Foxp3 in Treg, we generated TNFα−/−cpdm mice to suppress progression of dermatitis." (PMID 31462647, 2019). "Suppression of TNFα-mediated dermatitis led to marked rescue of Foxp3 expression in Treg, indicating that reducing the Foxp3+ T cell population in cpdm mice was a secondary effect with respect to chronic dermatitis." (PMID 31462647, 2019). "Although immunofluorescent staining was not performed in this study, our previous report demonstrated Foxp3/IL‐10 double‐positive cells by immunofluorescence in IMQ‐induced dermatitis treated with maxacalcitol, supporting the current immunohistochemical findings." (PMID 41137524, 2026). "In our model of dermatitis, we found that the HA receptor antagonists thioperamide and JNJ suppress the type 2 response (Th2/Tc2), which is associated with a higher proportion of FOXp3+ lymphocytes with functional activity, as we found inhibition of T-cell proliferation." (PMID 36275674, 2022). "Both indoles decreased the induction of IL-17 but promoted IL-10 and FoxP3 expression in mice expressing AHR, attenuating skin inflammation." (PMID 34831399, 2021). "Since NGO application constrains quantitative and qualitative alterations in Treg cells, such as a decreased Foxp3 and increased GATA3 expression during skin inflammation, it would be worthwhile to investigate whether NGO can regulate the progression of FA." (PMID 39199350, 2024). "FoxP3+ regulatory T cells were not affected by dermatitis induction and independent of GM, except for the vehicle treated CS-GM mice which had a lower proportion of regulatory T cells in ALN compared to vehicle treated VD-GM mice." (PMID 37889696, 2023). "HFD and oral propionate did not increase Foxp3 mRNA levels or number of Foxp3+ cells in imiquimod-induced dermatitis." (PMID 37762500, 2023). "It is hypothesized that propionate and HFD may not induce the generation of Foxp3+ Tregs in imiquimod-induced dermatitis, which might contain a large amount of IL-6, IL-1β, or IL-23 counteracting their generation." (PMID 37762500, 2023). "Interestingly, deletion of Brd4 in Foxp3+ Tregs, which also constitutively express OX40, compromised their suppressive functions, and this, in turn, contributed to the enhanced activation of γδ T cells, as well as the severity of dermatitis and hair follicle destruction." (PMID 36256455, 2022). "Importantly, mRNA levels of Foxp3, IL-10, and TGFβ were significantly decreased in TLR2 KO mice compared with WT mice, suggesting that downregulation of Tregs and impaired IL-10 production in TLR2 KO mice increased Th1 cytokine mRNA levels and exacerbated the imiquimod-induced skin inflammation." (PMID 33202847, 2020).
kidney transplant (23 papers, 2012 to 2025). A surgical procedure in which one or both kidneys from a donor are implanted into a recipient. "Here, we describe the expression of FOXP3 mRNA variants in healthy females and males, and in kidney transplant recipients (KTR)." (PMID 38802392, 2024). "In conclusion, low levels of peripheral blood Total FOXP3 mRNA transcript levels are associated with prolonged CRP elevation during active inflammatory responses in incident kidney transplant recipients." (PMID 37771580, 2023). "In this prospective investigation, the results show that lower levels of Total FOXP3 mRNA in peripheral blood mononuclear cells are significantly associated with prolonged inflammatory response to stimuli in kidney transplant recipients." (PMID 37771580, 2023). "Our prior work demonstrated that MDSCs stimulate Foxp3+ Treg proliferation via phosphorylation of the Stat3 pathway, thereby promoting colorectal carcinogenesis." (PMID 40969768, 2025). "Our results show that measurements of lower Total FOXP3 mRNA in peripheral blood mononuclear cells, before episodes of inflammatory response, are associated with prolonged elevation of CRP levels in kidney transplant recipients." (PMID 37771580, 2023). "Although we found an association between Total FOXP3 mRNA levels and prolonged CRP elevation during inflammatory responses, this association was found in incident kidney transplant recipients." (PMID 37771580, 2023). "Analysis between the groups of lip tumors with low/moderate vs. high expression of SMA showed a significant increase of the FOXP3+/CD8+ ratio in high SMA tumors (p = 0.02)." (PMID 36900270, 2023). "The ratio of mean fluorescence intensity (MFI) RORγT:FoxP3 activity was found to be ≤1 in the controls of our study population whereas this ratio was ≥1 in the kidney injury group." (PMID 34868786, 2021). "Several antibodies were found to deplete T-reg cells including basiliximab, a chimeric anti-CD25 monoclonal antibody, which was first tested in kidney transplant patients and showed a transitional loss of FOXP3+ and FOXP3− CD25+ T-cells in the circulation." (PMID 31547627, 2019). "To examine the effect of BLT versus CsA on the frequency of circulating Tregs in kidney transplant patients, we first analyzed the expression of FOXP3 in total CD4+ T cells." (PMID 28316600, 2017). "The loss of the T memory response following TBI was associated with a relative increase of CD4+CD25+ Foxp3+ expressing T regs, as compared to the CD8+ T effector cells requisite for skin graft rejection." (PMID 22723935, 2012). "This suggests that low levels of Total FOXP3 mRNA expression in kidney transplant recipients may lead to a decrease in T regulatory cell suppression of active inflammation." (PMID 37771580, 2023). "More importantly, low levels of Total FOXP3 mRNA in peripheral blood mononuclear cells may highlight kidney transplant recipients who may react to inflammatory stimuli with a prolonged inflammatory response." (PMID 37771580, 2023). "The transcription levels of IL-17F (a subfamily of IL-17), IL-23 (an inducing factor of IL-17A), and Foxp3 (a marker for regulatory T cells) were altered in the kidneys of both adenine-induced kidney injury groups; the levels were comparable between SPF and GF groups." (PMID 32859011, 2020). "As the percentage of CD25+FOXP3+ cells within the CD4+ subpopulation was reduced in kidney transplant patients, for the suppression assays a gate was set to sort Tregs containing >85% of CD4+CD25hiFOXP3+ T cells similar to the control group (CD4+CD25veryhi gate)." (PMID 28316600, 2017). "In kidney transplant recipients, studies have shown that recipients with higher levels of T-regulatory cells are less likely to experience allograft rejection, and that recipients with higher levels of FOXP3 show stable allograft function despite negligible immunosuppressive therapy." (PMID 38660296, 2024).
kidney transplant (continued). "Differences between tumor types were most pronounced for regulatory T-cells (Foxp3+ cells) with more than half of lung adeno (LUAD), head and neck squamous (HNSC), stomach adenocarcinoma (STAD) and esophageal (ESCA) cancer samples having Foxp3-hot topographies." (PMID 30179157, 2018). "Our results suggest that Helios expression is not responsible for the levels of FOXP3, as this marker was similarly downregulated in Helios+ and Helios− Tregs from kidney transplant patients, compared to controls." (PMID 28316600, 2017). "Given the development of spontaneous prostatitis in NOD mice, that have defective T-reg responses, and the demonstrated role of IL7 in switching from FoxP3+ve T-regs to IL17 producing cells, this hypothesis is under active investigation." (PMID 25933188, 2015).